IL6 (interleukin 6)
Diseases named in the same sentence as IL6 in open-access papers (continued):
Sharing a sentence is not in itself a finding about the gene and the disease.
infection (continued). "Higher mRNA levels of inflammatory cytokines IL-1β, IL-6, IL-8, and TNF-α were observed during early symptomatic infection (JM-1) compared to healthy controls." (PMID 34669281, 2021). "In BeWo trophoblast cells, the infection induces macrophage migration inhibitory factor (MIF), IL-12 and IL-6 production, and in HTR-8/SVneo trophoblast cells, T. gondii infection also increases the IL-6 production." (PMID 33912151, 2021). "On admission, the median of the infection parameters C‐reactive protein (CRP), interleukin (IL)-6, brain-type natriuretic peptide (BNP) and procalcitonin were above the normal range in the peripheral blood." (PMID 33666682, 2021). "The results showed that most inflammatory factors, including IL-1β, IL-6, IL-8, and TNF-α, were significantly increased after infection." (PMID 34593766, 2021). "Several chemokines were induced quickly in the early phase (day 2 p.i.)and maintained at a rather high level through the first week of infection, including CCL2, CCL3, CCL4, CCL7, CXCL10, IL-6, IFN-γ, CCL11, CCL5, TNF-α, CXCL1, IL-4, IL-12p70." (PMID 34379705, 2021). "Next, we detected the expression of IL-6, IL-1β and TNF-α in RAW264.7 cells after infection with the WT or ΔCRISPR strains." (PMID 34727007, 2021). "A cytometric bead array (CBA) was used to simultaneously determine the level of cytokines IL-6, IL-10, MCP-1, IFN-γ, TNF-α, and IL-12p70 in the serum of uninfected mice and mice infected with T. gondii at six-days post-infection." (PMID 34578186, 2021). "Accordingly, gene expression analysis revealed an early and significant induction of IL1A, IL6, and CXCL8 expression during infection of keratinocytes with S. aureus accounting for the detrimental effects observed." (PMID 34944618, 2021). "Compared with the normal control group, infection by ETEC K88 significantly increased serum TNF-α, IL-6, IL-1β, IFN-γ, VIP, sIgA and histamine levels, as well as the β-hexosaminidase, tryptase and MPO activities." (PMID 34899686, 2021). "The observed increased expression of IL-1β, IL-6, and IP-10 in DSS and DHF can be attributed to DENV E triggered cytokines, since majority of our samples are from primary infection." (PMID 34447698, 2021). "The mediators of acute inflammation and infection, such as CRP, IL-6, and PCT, have long been involved in the pathophysiology of critically ill patients and are routinely used for diagnostic, prognostic, and treatment monitoring in the ICU." (PMID 34749673, 2021). "The host cells (EA.hy926) responded to the infection with an increased gene expression of CCL5, ICAM-1, IL-6, and CXCL10." (PMID 34490828, 2021). "In the present study, plasma levels of HBP were positively correlated with the levels of N%, IL-6, CRP, D-dimer, PCT, and WBC, suggesting that HBP and other candidate mediators increase in response to infection and inflammation." (PMID 34778149, 2021). "Suggesting low systemic response, the blood of mice trained 9 weeks contained lower levels of a broad range of cytokines (IL-1β, IL-6, IL-10, IL-12p40, IL-17A, IL-18, IFNγ, TNF, CCL2 and CXCL5) 2 days after infection with L. monocytogenes." (PMID 34603295, 2021). "Again, B. dorei-treatment significantly reduced the levels of IL-1β, IL-6, TNF-α, IL-10, MCP-1 and IP-10 in lung compared with PBS-treated infection mice at day 7 p.i., to a comparable degree relative to the oseltamivi treatment." (PMID 35154087, 2021). "Proinflammatory cytokines, such as IL-1β, IL-6, IFNα/β, and TNFα, produced upon TMEV infection via TLR-mediated signals, further upregulate the production of chemokines." (PMID 34067536, 2021). "In contrast, the level of IL-6 induced in vivo by BS26 peaked at 34,690 pg/mL at 12 h post-infection and gradually decreased thereafter." (PMID 34357984, 2021). "Specifically in the module, we find genes induced in response to infection such as IL1B, TNF, IL6, IL12B, NFKBIA, JUN, and MAP3K8, which are related to Toll-like receptor signalling (Appendix B)." (PMID 33498280, 2021).
infection (continued). "Levels of G-CSF, IL-1β, IL-5, and IL-6, and chemoattractant VEGF were significantly altered during the acute phase of infection with concomitant detection of bacterial loads in the blood." (PMID 34451491, 2021). "To access the therapeutic roles of anti-cytokine mAb in vivo, we inoculated 5-day-old neonatal mice via i.m. with 104 TCID50 CVA2 and administered with isotype control, anti-TNF-α, anti-IL-6, and anti-MCP-1 mAbs via the i.p. route at 12 h post infection." (PMID 34122374, 2021). "When microglia are stimulated by infection, trauma and other harmful stimuli, they will activate them into M1 phenotype and release TNF-α, IL-6 and IL-12, among which TNF-α is one of the markers of M1 phenotype microglia." (PMID 34135761, 2021). "S. suis strain P1/7 was able to induce significantly more rapid production and higher levels of IL-6 and TNF-a early in the post-infection period, reaching peaks of 54,027 pg/mL and 2067 pg/mL at 8 h, respectively." (PMID 34357984, 2021). "The cytokine analysis revealed a significant increase in the level of serum IL-6, IL-10 and IFN-γ during the acute phase of the infection, but interestingly IL-10 lowered to normal upon clearance of the virus in the clinically recovered case." (PMID 34460819, 2021). "In conclusion, type I fimbriae, curli fimbriae, and flagella are involved in the release of IL-6 and IL-8 by cocultured HTB-5 and HMC-1 cells at 3 and 5 h after infection." (PMID 34835359, 2021). "The level of sIL-2R was positively correlated with CRP, SAA, IL-6, APACHE II, and the SOFA score in the infection group (r = 0.396, p < 0.001; r = 0.314, p < 0.008; r = 0.262, p = 0.028; r = 0.302, p = 0.011; and r = 0.348, p = 0.003, respectively)." (PMID 34745113, 2021). "On one hand, six of these biomarkers (CD14, HVEM, IL-6, B7.1, Siglec-10, and HIF-1α) were related to both HIV exposure and infection, presenting significantly higher expression in both the HIV+ and HEU groups than in the UU group." (PMID 34211989, 2021). "On the other hand, this inflammatory response was more efficiently regulated in the later stages of the infection, as evidenced by decreased levels of neutrophils, TNF-α, CCL2, and IL-6 and the increases in the regulatory cytokines IL-10 and IL-27." (PMID 34207076, 2021). "The secondary pro-inflammatory cytokine, IL-6, and a chemokine, RANTES, were shown to be produced during the late hours of infection 12 and 24 h with 1.25 mM LiCl being the most effective." (PMID 34088327, 2021). "After 48 h of infection with K. oxytoca AD3, the levels of IL-6 and TNF-α in the thymus, lung, spleen, kidney, and liver of mice increased significantly, while IL-10 decreased significantly, which was effectively alleviated via phage therapy." (PMID 34925270, 2021). "Our data showed that at day 50 of infection with S. mansoni increased circulating IFN-γ, IL-6 and TNF levels were observed in mice with adequate nutritional status." (PMID 33815321, 2021). "Consistently, Trim31−/− mice also had lower levels of IL-6 and TNF-α in the homogenates of kidney and liver after 5 days of infection with C. albicans." (PMID 34362877, 2021). "Consistent with the results obtained with VSV-GFP infection, we observed higher levels of PR8-GFP replication and lower levels of IL-6 and IFN-β secretion in FMDV VP3-expressing PK15 cells." (PMID 34578357, 2021). "Previous results indicate that infection by C. gattii induces the production of cytokines related to the Th1 profile more than other species of Cryptococcus, such as IL-1β, TNF-α and IL-6." (PMID 34526536, 2021). "During infection, activated macrophages secrete proinflammatory cytokines (e.g., TNF-α, IL-1β and IL-6) and inflammatory mediators (e.g., NO and PGE2) to regulate inflammatory responses against pathogens." (PMID 34564598, 2021).
infection (continued). "In turn, a dramatic rise in IL-1β, IL-6, and TNF-α plasma concentrations was evident 20 hours after infection in i.v. iron-treated Fth-KO animals as compared with control and iron-administered WT animals and control-treated FthΔ/Δ mice." (PMID 34236052, 2021). "Among the most notable differences were IL-6, CCL2, and CXCL10 (IP-10), at 4.1-, 2.3- and 2.1-fold higher levels, respectively, than those detected in response to the sublethal PVM infection." (PMID 33922096, 2021). "Contrary to the SARS-CoV-2 infection, infection with coronavirus infectious bronchitis virus (IBV) resulted in an increase in DUSP1 as viral defense mechanism to reduce p38 MAPK activation and IL-6 and IL-8 cytokine production." (PMID 33995033, 2021). "To date, few studies focused on the prediction of the severe and extremely severe infections based on CRP, IL-6, or NRL." (PMID 33575324, 2021). "In control animals, we noted a significant increase in proinflammatory cytokines (IL-1α, IL-1β, IL-6, and TNF-α), and chemokines (RANTES/CCL5 and CXCL1) coupled with the surge of G-CSF in response to infection." (PMID 33514747, 2021). "Infection of BMDM with the Δami1 mutant induced a prominently proinflammatory cytokine response, through increased secretion of IL-1α, IL-6, and IL-12p40." (PMID 33980132, 2021). "Further, the IL-6 mRNA expression in the trachea of group III was lower (p < 0.05) compared with levels in group I at day 3 and 7 post-infection." (PMID 34988139, 2021). "Our investigation showed that the increased levels of TNF-α, IL-6, and IL-β in LPS-induced RAW 264.7 were inverted after the infection with miR-31-5p mimic." (PMID 33710444, 2021). "This animal also had elevated plasma levels of two inflammatory markers, interleukin-6 (IL-6) and C-reactive protein (CRP), 2 days after infection." (PMID 34817208, 2021). "The mRNA expression levels of cytokines IL-2, IL-4, IL-6, IL-8, IL-10, IL-12p40, and IFN-γwere relatively different after P1 infection." (PMID 34988138, 2021). "For IL-6, H9N2 AIV infection increased its expression by 20 fold, and DATS treatment reduced it to 18 fold." (PMID 34412671, 2021). "During active infection, IFNα, IP10, IL6 and HGF showed a pleiotropic effect on several immune cells (top)." (PMID 34867943, 2021). "Patients hospitalized with severe influenza due to infection with avian H5N1 exhibit exacerbated levels of circulating pro-inflammatory cytokines including TNF-a, IL-6, and sIL-2r, IP-10, and MIG." (PMID 34959590, 2021). "WT-infection significantly upregulated the expression of gamma interferon (IFN-γ), IL-6, IL-10, and CXCL10 (also known as IP-10) in the lungs compared with that in S gene mutants." (PMID 34425707, 2021). "The challenge infection with 2 LD50 also resulted in similar results, with a marked reduction in IFN-γ and IL-6 being observed from HANA-VLP-immunized mice." (PMID 34684240, 2021). "Inflammation is a response against infection, illness and injury by the excessive expressions of chemokines and inflammatory cytokines such as TNF-α, IL-6 and IL-8." (PMID 33646441, 2021). "The results of IL-6, CCL2 and CXCL10 secretion from OT-infected HMECs at 8, 16, 24, and 48 hours post-infection were shown in." (PMID 34368012, 2021). "Nlrp3−/− mice infected with F. tularensis LVS had significantly higher levels of IL-1β, IL-6, IL-12p40, G-CSF, GM-CSF, TNF-α, and RANTES as compared to the wild-type mice on day 3 post-infection." (PMID 34690967, 2021). "The lung homogenates from Nlrp3−/− mice showed significantly higher levels of IL-1β, IL-6, IL-10, IL-12p70, G-CSF, GM-CSF, TNF-α, and RANTES than the wild-type mice on day 3 post-infection." (PMID 34690967, 2021). "IL-1β, IL-6, IL-8, MCP-1 and IFNγ, were previously reported to be elevated in lethal infection using a high dose of B. pseudomallei 1026b in AGMs." (PMID 33571211, 2021). "Increases in IL-15, IL-1β, IL-6, and TNF-α levels were slightly more delayed in the CSF, beginning closer to day 6 post-infection." (PMID 34001896, 2021).
infection (continued). "The mRNA levels of Nogo-A, CHOP, IL-6, and TNF-α were also significantly increased after infection with Ad-Nogo relative to the control (Ad-GFP)." (PMID 33572505, 2021). "As with infection with THP-1 macrophages, NuLi-1 cells infected with chronic P. aeruginosa isolates induced less IL-1β expression but more IL-6 expression, while the expression of TNF and IL-10 were undetectable (data not shown)." (PMID 33664232, 2021). "WT and Fpr2−/− bone marrow-derived macrophages (BMDMs) were infected with S. suis (initial multiplicity of infection [MOI] of 100), and IL-6 levels in the supernatant were measured at different time points (2, 8, and 12 h)." (PMID 33318141, 2021). "Impaired ATG16L1, IRGM or NOD2 expression in macrophages increases intracellular AIEC with enhanced secretion of IL-6 and TNF in response to infection." (PMID 33468624, 2021). "This was reflected in the induction of an enhanced inflammatory response in the early stages of infection characterized by increases in the numbers of macrophages and neutrophils as well as increases in the levels of IL-1β, IFN-γ, and IL-6." (PMID 34207076, 2021). "After adjusting for age and the sampling time after days of disease onset, IL-6, IL-8, MIP-1α, MIP-1β and IFN-γ were significantly, strongly positively correlated with each other early after infection at V1 timepoint." (PMID 33976217, 2021). "In our hands, nasally administered L. plantarum CRL1506 was able to increase the levels of IFN-α, IFN-β, IL-6, and IFN-γ in the broncho-alveolar lavages of mice after the nasal challenge with poly(I:C) or the infection with RSV." (PMID 34578229, 2021). "Yet, in vitro, VA1 infection at a high MOI significantly increased the production of IP-10 and IL-6 in primary astrocytes and immortalized glial cells and IL-8 in primary astrocytes and our studies show increased IL-8 expression." (PMID 33673521, 2021). "Per bin, the intron counts of the infection-induced genes IFIT2, OAS2, CCL5, IL6, NFKBIA, and TNF are shown, along with ATXN10 as control." (PMID 33585804, 2021). "In contrast, IL-4, IL-5, IL-6, and epidermal growth factor (EGF) reached peak levels late during infection, between 15 and 25 DPI, before dropping considerably at the terminal time point." (PMID 33436428, 2021). "Other possible facilitators of IL-17A expression include IL-6, as it is increased during MHV68 infection, or IL-21, as IL-21 signaling is required for efficient establishment of MHV68 latency and germinal center response in infected mice." (PMID 33824206, 2021). "Our results are also in line with a previous report demonstrating that following infection with HCoV-229E human macrophages strongly secrete TNF, but also produce IL-6 and some IFN-β." (PMID 33912475, 2021). "Our results showed that Tat-mutant infection can significantly induce the expression of TNF-α and IL-6." (PMID 34195100, 2021). "Analysis of cytokine and chemokines in serum showed a characteristic peak in IL-6, CCL2, CXCL10, and CXCL11 production at day 1 after virus inoculation as also described by others for H5N1 and pH1N1 infection." (PMID 33671829, 2021). "IL-6 and TNF-α play a key role in the physiological inflammatory response such as during infection, but also in several diseases where elevated levels of these cytokines are associated with a poor clinical outcome." (PMID 34564578, 2021). "Regarding the infection index, most patients had erythrocyte sedimentation rate (ESR), C-reactive protein (CRP), serum ferritin (SF) and interleukin-6 (IL-6) above the normal range." (PMID 33542448, 2021). "In Rwanda, Fractalkine, GMCSF, ITAC, IL-1ß, IL-6, IL-7, IL-8, MIP-1α, and TNFα concentrations were significantly increased in the pre-infection group compared to the uninfected group." (PMID 33731158, 2021). "Upon infection, IRF1 is first activated by PRR signaling and then sustained via autocrine/paracrine TNF-α and IL-6." (PMID 34607464, 2021).
infection (continued). "(A–C) Serum levels of inflammatory cytokines IL-1β (A), TNFα (B), and IL-6 (C) of young (6 months old) and old (24 months old) infected mice on day 8 post (PFU 7e2) infection." (PMID 34151773, 2021). "Meanwhile, GL or GM pre-infection treatments significantly (P < 0.05) decreased ST-induced pro-inflammatory cytokine (IFN-γ, TNF-α, and IL-6) expression in both spleen and liver and increased (P < 0.05) anti-inflammatory cytokine IL-10 secretion in spleen." (PMID 34239908, 2021). "This inhibitory action is later counteracted by the accumulation of circulating IL-6 and TNF-α which upregulate IL-10 production, hence explaining the rise of a second peak in IL-10 when the infection occurs at CT12." (PMID 33788832, 2021). "GTP vaccine strains infection alone can enhanced the mRNA expression of IL-1β, TNF-α, IL-6, IL-10, while the expression of IFN-α mRNA is inhibited." (PMID 33827620, 2021). "Next, the mRNA expression of IL-6 and IL-8 was measured to evaluate the induction of pro-inflammatory cytokines, and chemokines following the H5N6 AIVs infection." (PMID 33584629, 2021). "A majority of studies conclude that antibodies, driven by a TH2-like response, have a functional role in protection from infection, while TH1/TH17 cytokines such as IFN-γ, TNF-α, IL-17, and IL-6, have also been correlated with protection or bacterial killing." (PMID 34835150, 2021). "IL-6 and CRP as acute phase reactants are elevated in response to infection, with IL-6 as the main inducer of CRP expression." (PMID 34680581, 2021). "Mabs infection robustly increased the production of proinflammatory cytokines including TNF-α, IL-6, and IL-1β in BMDMs at 18 hpi." (PMID 34447358, 2021). "In the CF mice, within 48-h of B. pseudohinzii inoculation, there is a significant spike in IL-1β (p = 0.010), IFN-γ (p = 0.032), IL-6 (p = 0.019), and TNF-α (p = 0.040) serum levels, well beyond the infection naïve controls." (PMID 34475490, 2021). "IL-6, MCP-1, IL-1RA, and I-TAC showed similar changes throughout the course of infection, particularly in the one Josiah and three NML-33 infected animals, which had increased levels of all four at their terminal end points." (PMID 34634087, 2021). "A different pattern of cytokine production was observed in intestinal samples, with C. rodentium single infection leading to a modest increase in pro-inflammatory cytokines (TNF, IL-6, IFN-γ, and IL-17) and IL-10 in the colon and cecum." (PMID 33440153, 2021). "In our study the phosphorylation of NF-ĸBp65 enhanced expression of IL-6, TNF-α and IL-1β, 24 h post-infection." (PMID 34233673, 2021). "In this cohort, non-severe and severe groups showed significant differences in white blood cells, neutrophils, lymphocytes, basophils and platelets counts, as well as in infection related parameters such as CRP and serum cytokine IL-6." (PMID 33504359, 2021). "Using the multiplex assays, we found that infection of 3-D cervical cell models with M. mulieris significantly upregulated expression of IL-6 (p<0.0001), IL-8 (p<0.0001), MCP-1 (p<0.01) and TNF-α (p<0.01) whereas infection with Eggerthella sp." (PMID 35004344, 2021). "To determine the role of TNC in the development of systemic inflammation, we measured the plasma levels of TNF-α, IL-6, and CCL2 as markers of systemic inflammation 24 and 42 h after the beginning of infection." (PMID 33776992, 2021). "In addition, we found a positively correlation between the duration of symptoms to ICU admission and the peripheral IL-6 values, to strengthen the hypothesis that in this second phase of infection the role of blood immunological markers and BALF cellularity are the main authors." (PMID 33858331, 2021). "We found that the mRNA expression of IFN-β and IL-6, which are vital antiviral modulators of innate immune response, significantly increased in DDX5-knockdown MEFs at 6 and 12 h post-infection (hpi) with VSV." (PMID 33909701, 2021).